MYO5B (myosin VB)
Description:
May be involved in vesicular trafficking via its association with the CART complex. The CART complex is necessary for efficient transferrin receptor recycling but not for EGFR degradation. Required in a complex with RAB11A and RAB11FIP2 for the transport of NPC1L1 to the plasma membrane. Together with RAB11A participates in CFTR trafficking to the plasma membrane and TF (transferrin) recycling in nonpolarized cells. Together with RAB11A and RAB8A participates in epithelial cell polarization. Together with RAB25 regulates transcytosis. Required for proper localization of bile salt export pump ABCB11 at the apical/canalicular plasma membrane of hepatocytes.
Synonyms: KIAA1119; DIAR2; MVID1; PFIC10
Tractability: Small molecule: a structure with a bound ligand is known. Antibody: the Human Protein Atlas places it where antibodies can reach. PROTAC: ubiquitination databases record sites on it; its protein half-life has been measured.
Gene: Protein-coding gene on chromosome 18 (49,822,789 to 50,195,164, reverse strand). Ensembl gene ENSG00000167306.
Subcellular location: Cytoplasm
Subcellular location (Human Protein Atlas): Plasma membrane
Pathways (Reactome):
Transport of small molecules: Vasopressin regulates renal water homeostasis via Aquaporins
Gene Ontology:
Molecular function: protein binding; small GTPase binding; actin filament binding; microfilament motor activity; ATP binding; cytoskeletal motor activity
Biological process: endosomal transport; vesicle-mediated transport; endocytosis; renal water homeostasis
Cellular component: apical cortex; extracellular exosome; protein-containing complex; actin cytoskeleton; cytoplasm; cytoplasmic vesicle membrane; recycling endosome; myosin complex
Genetic constraint (gnomAD): Loss-of-function variants: 139 observed, 226.31 expected, observed/expected ratio (o/e) 0.61, 90% interval 0.53 to 0.71. The upper end of that interval is the gene's LOEUF score, 0.71, which puts it in group 2 of 6, group 1 being the genes least tolerant of losing a copy. Missense variants: 2,290 observed, 2,365.7 expected, observed/expected ratio (o/e) 0.97, 90% interval 0.93 to 1. Synonymous variants: 906 observed, 910.38 expected, observed/expected ratio (o/e) 1, 90% interval 0.94 to 1.05.
Homologues: Orthologues: chimpanzee MYO5B (99% identical), macaque MYO5B (98% identical), pig MYO5B (94% identical), rabbit MYO5B (91% identical), dog MYO5B (90% identical), mouse Myo5b (90% identical), guinea pig MYO5B (89% identical), rat Myo5b (89% identical), tropical clawed frog myo5b (77% identical), zebrafish myo5b (72% identical). Paralogues in human: MYO5A (63% identical), MYO5C (48% identical), MYH3 (26% identical), MYH7B (26% identical), MYH2 (26% identical), MYH7 (26% identical), MYH8 (26% identical), MYH4 (25% identical), MYH6 (25% identical), MYH1 (25% identical), MYH10 (25% identical), MYH13 (25% identical), and 32 more.
Diseases named in the same sentence as MYO5B in open-access papers:
MYO5B is named in the same sentence as 81 diseases in open-access papers, as found by Europe PMC text mining. Sharing a sentence is not in itself a finding about the gene and the disease. The quoted sentences say what the papers report.
microvillus inclusion disease (35 papers, 2011 to 2026). Microvillus inclusion disease (MVID) is a very rare, severe, malabsorbative syndrome characterized clinically by protracted or intractable neonatal secretory diarrhea and histologically by inclusion bodies on the intestinal epithelium. "Newly discovered mutations in the myosin Vb (MYO5B) gene have been identified as causative factor for microvillus inclusion diseases." (PMID 37691828, 2023). "This unconventional myosin orchestrates apical trafficking and microvillus differentiation in enterocytes, and LoF MYO5B mutations are a well-known cause of microvillus inclusion disease (MVID)." (PMID 35575086, 2022). "Mutations in the MYO5B gene are associated with the microvillus inclusion disease (MVID), a congenital disorder of the enterocyte that leads to intractable diarrhoea." (PMID 35884482, 2022). "Microvillus inclusion disease (MVID) is a rare enteropathy caused by mutations in the MYO5B or STX3 gene." (PMID 34501384, 2021). "MYO5B variants can also cause microvillus inclusion disease (MVID), a severe congenital diarrheal and malabsorption disorder requiring life-long total parenteral nutrition." (PMID 33557414, 2021). "Mouse models for MYO5B-deficiency have been generated and the predominant symptom in this model is Microvillus Inclusion Disease (MID)." (PMID 33383947, 2020). "Inherited MYO5B mutations have recently been associated with microvillus inclusion disease (MVID), an autosomal recessive syndrome characterized by intractable, life-threatening, watery diarrhea appearing shortly after birth." (PMID 26201991, 2015). "Loss of functional myosin Vb has also been identified recently as the key mutation in neonates with microvillous inclusion disease (MVID)." (PMID 21063400, 2011). "Total parenteral nutrition (TPN) dependency (typically cases of MYO5B variant-associated microvillus inclusion disease (MVID)) was an exclusion criterion as BSEP expression may be affected by long-term TPN." (PMID 41511375, 2026). "Likewise, another study has the same implications as previous studies; MYO5B (myosin 5B) mutation-induced microvillus inclusion disease (MVID) causes fatal autosomal recessive congenital diarrheal disorders." (PMID 37691828, 2023). "The genetic defect of MYO5B is usually associated with microvillus inclusion disease (MVID)." (PMID 34900494, 2021). "Most MYO5B-deficient patients dominantly suffer from Microvillus Inclusion Disease." (PMID 33383947, 2020). "This work was inspired by several earlier observations of cholestatic liver disease in patients with microvillus inclusion disease (MVID), a genetic disease also caused by variants in the MYO5B gene." (PMID 40355967, 2025). "One such example is microvillus inclusion disease (MVID), a congenital enteropathy characterized by early-onset diarrhea, caused by mutations in myosin 5b (MYO5B), STX3 or syntaxin binding protein 2 (STXBP2)." (PMID 38799985, 2024). "Functional loss of the motor protein myosin Vb (MYO5B) induces various defects in intestinal epithelial function and causes a congenital diarrheal disorder, namely, microvillus inclusion disease (MVID)." (PMID 39404772, 2024). "Microvillus inclusion disease (MVID) is associated with specific variants in the MYO5B gene causing disrupt epithelial cell polarity." (PMID 37200712, 2023). "Microvillus inclusion disease (MVID) is a lethal inherited diarrheal disease of newborns resulting from loss of function mutations in the actin motor myosin VB (MYO5B)." (PMID 35887942, 2022). "Microvillus inclusion disease (MVID), a lethal congenital diarrheal disease, results from loss of function mutations in the apical actin motor myosin VB (MYO5B)." (PMID 35887942, 2022). "Functional loss of myosin Vb (MYO5B) induces a variety of deficits in intestinal epithelial cell function and causes a congenital diarrheal disorder, microvillus inclusion disease (MVID)." (PMID 34197342, 2021).
microvillus inclusion disease (continued). "Biallelic MYO5B mutations are identified in the majority of patients with microvillus inclusion disease (MVID)." (PMID 33525641, 2021). "Mutations in the actin motor protein myosinVb (myo5b) cause aberrant apical cargo transport and the congenital enteropathy microvillus inclusion disease (MVID)." (PMID 33924896, 2021). "Loss-of-function mutations in MYO5B are common in microvillus inclusion disease (MVID) and cause disruption of cell polarity." (PMID 32511227, 2020). "Mutations in recycling endosome–associated and MYO5B-encoded myosin Vb protein can cause progressive familial intrahepatic cholestasis and/or microvillus inclusion disease (MVID)." (PMID 31682603, 2019). "Mutations in the MYO5B gene have been previously implicated in human diseases including microvillus inclusion disease (MVID) in newborns." (PMID 27242896, 2016). "Microvillus inclusion disease (MVID) is a rare congenital diarrheal disorder typically caused by loss of function mutations in the unconventional myosin, myosin 5b (MYO5B), which leads to the mistrafficking of apical components in enterocytes." (PMID 39978676, 2025). "Moreover, loss-of-function mutations in the MYO5B gene lead to Microvillus inclusion disease (MVID) in humans." (PMID 39661054, 2025). "Congenital diarrhea and intrahepatic cholestasis are also the prime symptoms in patients with microvillus inclusion disease (MVID) and mutations in MYO5B, encoding the recycling endosome–associated myosin Vb." (PMID 35421597, 2022). "Taken together, our results provide evidence that UNC45A plays an essential role in epithelial morphogenesis through its cochaperone function of myosin VB and that UNC45A loss causes a variant of microvillus inclusion disease." (PMID 35575086, 2022). "We recently reported that tuft cell differentiation was specifically inhibited by myosin Vb (MYO5B) loss, a model of a congenital diarrheal disorder, microvillus inclusion disease." (PMID 34835968, 2021). "In conclusion, we describe here the phenotype of Myo5b knockout mice, which closely phenocopies human early-onset microvillus inclusion disease." (PMID 26201991, 2015). "Microvillus inclusion disease (MVID), caused by loss-of-function mutations in the motor protein myosin Vb (MYO5B), is a severe infantile disease characterized by diarrhea, malabsorption, and acid/base instability, requiring intensive parenteral support for nutritional and fluid management." (PMID 37643022, 2023). "Myosin Vb (MYO5B) is an essential motor protein for apical membrane protein trafficking, and its inhibition through truncation or missense mutations causes the congenital diarrheal disorder microvillus inclusion disease (MVID)." (PMID 34197342, 2021). "Mutations in MYO5B encoding Myosin 5b, which acts as a molecular motor not only for Rab11a, but also Rab11b, Rab25, and Rab8, cause MicroVillus Inclusion Disease (MVID) in which malabsorption results from the absence of the intestinal brush border." (PMID 26116792, 2015). "Inborn errors of myosin 5b (MYO5B), a gene coding for an enterocyte vesicular motor protein that interacts with Rab proteins, lead to microvillus inclusion disease (MVID), characterized by the absence of microvillus formation, which results in severe neonatal secretory diarrhea." (PMID 40649913, 2025).
cholestasis (21 papers, 2018 to 2026). Impairment of the bile flow caused by obstruction within the liver, or outside the liver in the bile duct system. "Several cases of MYO5B-associated cholestasis showed a normal canalicular BSEP staining pattern, while other cases displayed an abnormal pattern described as “reduced staining”, “intracellular” or “sub-canalicular” staining." (PMID 41511375, 2026). "Supported by these observations, the pathological mechanism of MYO5B-associated cholestasis has been attributed to aberrant BSEP trafficking." (PMID 41511375, 2026). "The majority of patients with MYO5B-associated cholestasis carried at least one missense variant (78%) or biallelic missense variants (47%) in the MYO5B gene." (PMID 41511375, 2026). "We found that approximately one-third of patients with MYO5B-associated cholestasis carried the p.(Arg824Cys) and/or p.(Arg92Cys) variant." (PMID 41511375, 2026). "Of these, MYO5B-associated cholestasis (OMIM#619868) emerges as a considerable group, estimated to represent up to 25% of FIC cases other than those caused by variations in the ATP8B1, ABCB11 and ABCB4 genes." (PMID 41511375, 2026). "The short median follow-up time of patients with MYO5B-associated cholestasis (3.35 months; due to the only recent discovery of MYO5B-associated cholestasis) prohibited long-term native liver survival analyses." (PMID 41511375, 2026). "The mechanism underlying MYO5B-associated cholestasis has been attributed to abnormal localization of BSEP in liver cells, essentially mimicking ABCB11 deficiency-associated FIC." (PMID 41511375, 2026). "p.(Arg824Cys) and p.(Arg92Cys) are not involved in interactions with other amino acids known to be mutated in MYO5B-associated cholestasis." (PMID 41511375, 2026). "The prevailing theory for the mechanism underlying MYO5B-associated cholestasis implicates faulty trafficking of the ABCB11-encoded bile salt export pump (BSEP) in hepatocytes due to dysfunctional myosin-Vb." (PMID 41511375, 2026). "MYO5B-associated cholestasis differed significantly from FIC(1/1) with regard to age of onset and serum bile acids, from FIC(1/3) with regard to age of onset, ALT and serum bile acids, and from FIC(3/3) with regard to ALT and GGT." (PMID 41511375, 2026). "Unique hits were screened for reports of cases that were diagnosed with MYO5B-associated cholestasis." (PMID 41511375, 2026). "We compared the serum biochemistry and clinical data of MYO5B-associated cholestasis with data from the ABCB11 deficiency-associated cholestasis database (NAPPED)." (PMID 41511375, 2026). "Nonetheless, only 6% of MYO5B-associated cholestasis cases underwent liver transplantation before the age of five years, less than reported for ABCB11 deficiency-associated cholestasis (FIC1/1 10%, FIC3/3 60% and FIC1/3 85%)." (PMID 41511375, 2026). "Further, expression of a human MYO5B variant in the mouse liver causes cholestasis and aberrant BSEP localization in the hepatocytes." (PMID 41511375, 2026). "The Myosin 5B (MYO5B) gene is primarily involved in cell motility and material transport which is associated with congenital intractable diarrhea and cholestasis." (PMID 39014344, 2024). "The researchers found that mutations in a gene called MYO5B were responsible for cholestasis and congenital diarrhea." (PMID 37324459, 2023). "To address this issue, we collected MYO5B noncanonical variants with uncertain significance both from the literature and new patients with suspected MYO5B-associated low GGT cholestasis." (PMID 40225142, 2023). "Based on all clinical features and laboratory evaluation, a diagnosis of MYO5B gene mutation leading to infantile cholestasis presenting with PFIC phenotype was made." (PMID 36705120, 2022). "The p.P660L mutation represents a known founder mutation among Navajo Indian patients with MVID and cholestasis, i.e., MYO5B-MIXED, and was counted only once in this study." (PMID 33525641, 2021).
cholestasis (continued). "In this report, we discuss the case of a nine-month-old girl with low-GGT cholestasis whose next-generation sequencing (NGS) showed a homozygous splicing variation (c.3045+3A>T) on the MYO5B (NM_001080467) gene, which was a novel mutation." (PMID 34900494, 2021). "The p.(Arg824Cys) variant caused cholestasis when overexpressed in Myo5b-knockout mouse livers." (PMID 41511375, 2026). "Hence, the p.(Arg824Cys) and p.(Arg92Cys) variants are highly prevalent and specific for MYO5B-associated cholestasis." (PMID 41511375, 2026). "Despite its prevalence, there has been limited examination of the biochemical and clinical aspects of MYO5B-associated cholestasis, and its clinical and mechanistic relationship with other FIC types remains unclear." (PMID 41511375, 2026). "They showed for the first time that MYO5B deficiency may lead to isolated cholestasis and that the MYO5B gene could be considered an additional PFIC locus." (PMID 35884482, 2022). "This case reports an unusual cause of cholestasis due to a mutation in the MYO5B gene." (PMID 36705120, 2022). "By contrast, the expression of a cholestasis-associated missense myosin Vb mutant (myosin Vb-P660L) or the expression of motorless mutants that expressed only the RAB11A-binding tail domain caused the mislocalization of these bile canalicular transporters, in agreement with an earlier report." (PMID 33557414, 2021). "Whether cholestasis in MVID patients is due to their MYO5B variants or is iatrogenic (e.g., due to total parenteral nutrition) is not clear." (PMID 33557414, 2021). "Interestingly, patients with nonsense mutations presumably merely cause MVID enteropathy, while only patients with missense mutations in MYO5B develop cholestasis." (PMID 33924896, 2021). "However, in other case reports of MYO5B-associated cholestasis, BSEP IHC results showed normal BSEP expression at the bile canalicular membrane, which may challenge this proposed mechanism." (PMID 41511375, 2026). "Hence, target gene sequencing can help diagnose the cause of cholestasis and detect variants of mutation potentially leading to the phenotype as in this report with compound heterozygous mutation in the MYO5B gene detected for the first time in the Nepali population." (PMID 36705120, 2022). "As only specific missense mutations in the motor domain of MYO5B cause cholestasis, gene addition therapy of such a smaller splice variant, if functional, may in theory be an option, but only in combination with deleting the expression of the endogenous mutated MYO5B protein." (PMID 33383947, 2020). "All published reports were retrieved from the MEDLINE database using the search string “((MYO5B OR myosin-Vb) AND cholestasis)”." (PMID 41511375, 2026). "Together, disease parameters from the MYO5B-associated and ABCB11 deficiency-associated cholestasis cohorts displayed significant differences, indicating a potentially distinct underlying cause." (PMID 41511375, 2026). "If a deficiency in BSEP were the major cause of MYO5B-associated cholestasis, we would expect the clinical parameters of MYO5B-associated and ABCB11 deficiency-associated cholestasis to be similar." (PMID 41511375, 2026). "Another value for NGS in early onset cholestasis is to identify the defect causing low-GGT PFICs (PFIC1, PFIC2, PFIC4 and the recently discovered MYO5B-associated cholestasis (PFIC10)." (PMID 41165782, 2025). "NR1H4 gene mutations cause PFIC5, while those in the MYO5B gene generate PFIC6 or MYO5B-related cholestasis." (PMID 39697951, 2024). "Our patient had most of the clinical and biochemical features in addition to the observed genetic variation to help us diagnose MYO5B cholestasis." (PMID 36705120, 2022). "The cholestasis results from the impairment of the MYO5B/RAB11A apical recycling endosome pathway in hepatocytes, the altered targeting of BSEP to the canalicular membrane and the increased ileal bile acid absorption." (PMID 30364420, 2018).